POSTN (periostin)
Diseases named in the same sentence as POSTN in open-access papers (continued):
Sharing a sentence is not in itself a finding about the gene and the disease.
ovarian carcinoma (84 papers, 2006 to 2025). A malignant neoplasm originating from the surface ovarian epithelium. "Periostin (POSTN), a secreted matricellular protein, is implicated in tumor progression and poor prognosis across diverse malignancies, including ovarian cancer." (PMID 40963633, 2025). "POSTN, by augmenting M2 macrophages and cancer-associated fibroblasts, facilitated ovarian cancer metastasis." (PMID 39494300, 2024). "POSTN is implicated in promoting metastasis of ovarian cancer via its ability to enhance M2 macrophages and cancer-associated fibroblasts through integrin-mediated activation of the NF-κB and TGF-β2 signaling pathways." (PMID 37180146, 2023). "For example, TGF-β1 can induce matrix POSTN to promote the migration and invasion of ovarian cancer, while the loss of PRC2 can affect the progression of prostate cancer." (PMID 37370795, 2023). "Periostin is a secretory protein that is overexpressed by stromal fibroblasts in multiple cancers, including ovarian cancer, and its overexpression is associated with poor clinical outcomes in patients with epithelial ovarian cancer." (PMID 36831623, 2023). "The CAF-derived ligand POSTN found in our study was previously associated with chemoresistance in ovarian cancer." (PMID 36352420, 2022). "In several malignant tumors, such as colorectal cancer, ovarian cancer, and hepatocellular carcinoma, high POSTN expression was confirmed to be associated with poor prognosis." (PMID 35559040, 2022). "In fact, patients with HGSOC associated with high stromal POSTN expression were found to have a worse prognosis, further elucidating the importance of CAFs in ovarian cancer progression." (PMID 35574025, 2022). "Upregulation of POSTN associates with increasing cell migration, chemoresistance and poor prognosis in various human cancers including ovarian cancer." (PMID 36550569, 2022). "The prognostic potential of PPIC was shown in high-grade glioma and in ovarian cancer PPIC was co-expressed with a gene signature associated with periostin, a gene product with reported roles in metastasis and angiogenesis." (PMID 34073412, 2021). "Elevated levels of TGFBI have been associated, in common with its paralogue POSTN, with poor survival in patients with ovarian cancer." (PMID 34561272, 2021). "Growing evidence has implicated that POSTN is overexpressed in various types of human cancer tissues, including ovarian cancer, breast cancer, colon cancer, head and neck cancer, and pancreatic ductal adenocarcinoma." (PMID 32987711, 2020). "In two independent ovarian cancer studies, periostin expression in tumor stroma was associated with chemotherapy resistance." (PMID 31412536, 2019). "In epithelial ovarian cancer patients, stromal expression of periostin was associated with cisplatin resistance and clinical treatment outcomes." (PMID 30927928, 2019). "Another study on epithelial ovarian cancer revealed association of strong expression of periostin with a poor prognosis, and platinum resistance and correlation with the FIGO stage (fr." (PMID 31412536, 2019). "An in vitro study revealed that periostin caused persistent activation of AKT in A2780 ovarian cancer cells, leading to cell survival under cisplatin treatment." (PMID 30927928, 2019). "In contrast, for periostin, loss of both Syndecan-1 and Syndecan-4 negatively affects ovarian cancer cell adhesion, which supports the notion that periostin utilizes a distinct mode of cellular interaction." (PMID 22640878, 2012). "It was reported that periostin can enhance the stemness of ovarian cancer cells, which may be a crucial factor in the high expression of periostin that is associated with aggressive cancer characteristics." (PMID 39941916, 2025). "POSTN, a matricellular protein implicated in gliomas and ovarian cancer, drives tumor growth and metastasis, influences cell responses,and could serve as a potential biomarker for GBM survival prognosis." (PMID 39315277, 2024).
ovarian carcinoma (continued). "We confirmed that DDR2 regulates POSTN expression in ovarian cancer-associated fibroblasts (CAFs)." (PMID 35884543, 2022). "In a risk prediction model of ovarian cancer, POSTN combined with two other markers had high prognostic accuracy, and another study found that polycystic ovary syndrome is associated with elevated POSTN levels." (PMID 33488671, 2020). "Both TGFBI and periostin have been implicated in ovarian cancer." (PMID 22640878, 2012). "These M2 macrophages and CAFs contribute to a tumor microenvironment that promotes immune evasion and metastasis, making POSTN a potential therapeutic target in ovarian cancer." (PMID 40330466, 2025). "Another key example of this NF-κB-driven interplay between ovarian cancer cells, macrophages, and the tumor microenvironment is seen with periostin (POSTN), a matrix protein overexpressed in highly invasive ovarian cancer cells." (PMID 40330466, 2025). "Through bindings to integrins αVβ3 and αVβ5, POSTN can activate the ERK/NF-κB signalling pathway in ovarian cancer cells, leading to increased expression of cytokines that promote macrophage mobility and polarization toward the M2 phenotype." (PMID 39780187, 2025). "Periostin (POSTN) is a secreted matricellular protein that is critical in promoting ovarian cancer metastasis." (PMID 40330466, 2025). "In ovarian cancer, POSTN enhances integrin β3 and β5 signaling, which activates ERK and NF-κB pathways in tumor cells." (PMID 40330466, 2025). "By activating the PI3K/AKT pathway and inducing EMT, CAFs-derived POSTN promotes the migration and invasion of ovarian cancer cells, thus leading to a poor prognosis." (PMID 38601538, 2024). "In the current study, we used established ovarian cancer cell lines to study the role of periostin in epithelial ovarian cancer." (PMID 38049490, 2023). "We found that POSTN frequently exhibits higher expression in recurrent relative to matched primary ovarian cancers." (PMID 38049490, 2023). "In fact, several recent studies have gradually reported the role of periostin in regulating macrophages in other diseases, such as glioblastoma, spinal cord injury, and ovarian cancer." (PMID 37047322, 2023). "Previous studies reported that periostin secreted by tumour cells acted as a chemoattractant to enhance the recruitment and polarization of M2 TAMs in glioblastoma and ovarian cancer through periostin‐integrin mediated signaling." (PMID 38115703, 2023). "We found that a periostin-high environment increased cancer stemness in ovarian cancer, evidenced by an increase in the CSC side population and by the expression of an established OC CSC marker, CD133, providing a link between TME factors and CSC behavior." (PMID 38049490, 2023). "Here we used in vitro and in vivo models to examine the role of exogenous periostin in ovarian cancer cell phenotypes, including growth, stemness, and chemosensitivity." (PMID 38049490, 2023). "TGF-β modulates periostin expression and promotes ovarian cancer growth and chemotherapy resistance." (PMID 36831623, 2023). "In an orthotopic mouse model of ovarian cancer where cancer cells are engineered to express POSTN resulted in potent tumor angiogenesis and metastasis." (PMID 36550569, 2022). "Whereas, periostin, overexpressed in the advanced and recurrent ovarian cancers, promotes adhesion, migration, and invasion in ovarian cancer and the human umbilical vein endothelial cells." (PMID 35740424, 2022). "In conclusion, we have identified that DDR2-expressing CAFs regulate POSTN through ITGB1 to promote tumor metastasis in ovarian cancer." (PMID 35884543, 2022). "We also found that elevated POSTN expression correlated with advanced stages of ovarian cancer and patient survival." (PMID 36550569, 2022). "Targeting POSTN using its binding DNA aptamer or neutralizing antibody significantly inhibits breast and ovarian cancer cell metastasis." (PMID 36550569, 2022).
ovarian carcinoma (continued). "In ovarian cancer, CAFs were shown to be responsible for the deposition of POSTN, which was able to decrease cisplatin-induced apoptosis potentially through the PI3K/AKT signaling pathway." (PMID 36550569, 2022). "Using isogenic pairs of low and highly invasive human ovarian cancer lines, we identified POSTN to be involved in regulating ovarian cancer cell growth and metastasis." (PMID 36550569, 2022). "We identify that the interaction between DDR2 and POSTN is important in CAFs and promotes tumor metastasis in ovarian cancer." (PMID 35884543, 2022). "SN50, an inhibitor against NF-κB nuclear translocation, was able to inhibit POSTN-induced cytokine production in the ovarian cancer cells." (PMID 36550569, 2022). "POSTN is overexpressed in many human cancers, including ovarian cancer, head and neck cancer, and pancreatic ductal cancer." (PMID 35832544, 2022). "Microarray and bioinformatics analysis of low and highly invasive ovarian cancer cell lines were used to reveal periostin (POSTN), a matrix protein with multifunctions in cancer, with elevated expression in the highly invasive cells." (PMID 36550569, 2022). "To explore the potential role of POSTN in CAF activation in ovarian cancer, we focused on examined the possible regulation of TGFβ, which is known to promote CAFs, by POSTN." (PMID 36550569, 2022). "Correlations between POSTN expression levels and clinical characteristics were analyzed using the Oncomine, commercial ovarian cancer cDNA and China Medical University Hospital patient cohort." (PMID 36550569, 2022). "Overall, the present study unveiled the POSTN-mediated interplay between ovarian cancer cells and stroma including monocytes and CAFs, and elucidated the underlying mechanism involved in cancer progression and metastasis." (PMID 36550569, 2022). "In ovarian cancer, high level of POSTN in ovarian cancer ascites fluids correlates with CD163 + TAMs infiltration and poor relapse-free survival in patients." (PMID 36550569, 2022). "To determine if DDR2 protein expression was correlated with POSTN protein expression in ovarian cancer patients, we performed immunohistochemistry on a tumor microarray with specimens from 180 patients with primary and metastatic tumor sites." (PMID 35884543, 2022). "The results suggest that autocrine effect of POSTN induces TGF-β2 expression from ovarian cancer cells to promote activation of normal stromal fibroblasts to become CAFs in metastatic tumors." (PMID 36550569, 2022). "Stromal DDR2 protein expression was highly correlated with stromal POSTN protein expression in ovarian cancer patients (Spearman rho = 0.77, p < 0.0001)." (PMID 35884543, 2022). "Other soluble ECM proteins, such as vitronectin (the 11th), SERPIND1 (the 38th), and periostin (the 112th), also exhibit different oncogenic activities in ovarian cancer." (PMID 35740424, 2022). "Our study elucidated the POSTN-mediated interplay between ovarian cancer cells and stroma to promote tumor growth and metastasis." (PMID 36550569, 2022). "Our study suggests that POSTN not only can serve as a prognosis marker, but also a therapeutic target for ovarian cancer." (PMID 36550569, 2022). "The results of the study suggested that periostin promotes invasiveness and migration of ovarian cancer cells in an αVβ3 and αVβ5-dependent manner." (PMID 34503128, 2021). "Of special attention is the description of the expression levels of genes such as POSTN, CHI3L1, CAV-1, IRS1, DCN, which according to literature data are associated with diseases such as POI, PCOS, and ovarian cancer." (PMID 34827207, 2021). "Elevated expression of fibronectin and periostin was also more common in fallopian cancers than in ovarian cancers." (PMID 31936272, 2020). "Both analyzed proteins, fibronectin and periostin, are engaged in similar cellular processes and are indicated as related to the survival of ovarian cancer patients." (PMID 31936272, 2020).
ovarian carcinoma (continued). "Periostin expression is markedly upregulated in various human tumors, including in head and neck, breast, colon, pancreatic, and ovarian cancers." (PMID 31918919, 2020). "Our results support some previous observations that fibronectin and periostin have a prognostic significance in ovarian cancer." (PMID 31936272, 2020). "The protein expression of POSTN was first evaluated in the series of 108 ovarian cancer samples (mainly HGSOC) for which we had complete clinico-pathological data, including survival (see chapter 2.2)." (PMID 31936272, 2020). "Our results indicate that fibronectin and periostin have a prognostic significance in ovarian cancer." (PMID 31936272, 2020). "Tissue arrays (US Biomax, Inc.)were used to asses periostin expression in different stages of progression of ovarian and fallopian tube epithelial tumors and different histological types of ovarian cancer." (PMID 31936272, 2020). "These experiments showed that elevated expression of fibronectin and periostin was more common in fallopian than in ovarian cancers." (PMID 31936272, 2020). "Both fibronectin and periostin have been suggested to be related with the survival of ovarian cancer patients." (PMID 31936272, 2020). "There are additional higher molecular weight bands reacting bound by E-PHA indicating that other glycoproteins were isolated with periostin that also carry this form of glycosylation in ovarian cancer cells." (PMID 30911061, 2019). "Periostin expression was also correlated with chemoresistance in two independent ovarian cancer studies." (PMID 31412536, 2019). "In ovarian cancer tissues our previous studies indicate that periostin displays truncated, agalactosylated, asialylated N-glycan structures with or without core fucose." (PMID 30911061, 2019). "Our analysis of secreted and membrane proteins from primary ovarian cancer tissues led to the discovery of periostin, also known as osteoblast-specific factor 2 (OSF-2) as a potential biomarker." (PMID 30911061, 2019). "Periostin is a glycoprotein with high expression in many tumors of epithelial origin including ovarian cancer." (PMID 30911061, 2019). "For example, POSTN has been shown to support adhesion and migration of ovarian epithelial cancer cells by interacting with αvβ3 and αvβ5 integrins and thus cells cultivated on POSTN showed more motility than cells cultivated on fibronectin." (PMID 29946533, 2018). "Periostin is expressed a high levels in tumor stroma and in cancer epithelial cells in ovarian cancer." (PMID 29946533, 2018). "On the contrary, the ovarian cancer cell lines showed a marked increase in the periostin concentration after incubation with HS5 after 48 h (18.3±16.3 ng/ml, P=0.023) but not after 24 h (1.54±0.50 ng/ml)." (PMID 27716740, 2016). "Taken together, POSTN expression in cancer stromal cells can be served as a poor prognostic marker for epithelial ovarian cancer." (PMID 26716408, 2016). "However, an increasing number of evidences showed that POSTN expressed in the cancer microenvironment was also associated with poor prognosis in various types of cancer such as non-small cell lung cancer, pancreatic cancer, prostate cancer as well as ovarian cancer." (PMID 26716408, 2016). "By analyzing public available microarray datasets, we identified that periostin (POSTN) was overexpressed in cancer stroma in epithelial ovarian cancer (EOC) patients." (PMID 26716408, 2016). "Further study is needed to investigate the relationship between POSTN in tumor microenvironment and ovarian cancer stem cell properties." (PMID 26716408, 2016). "Periostin-deficient animal models demonstrate delayed wound repair and periostin has been described as a novel pro-angiogenic factor leading to significant enhancement of angiogenesis in human breast, gastric and ovarian cancer." (PMID 25369801, 2015). "Periostin is secreted by ovarian cancer, similar to TGFBI, and promotes integrin-mediated cell motility." (PMID 22640878, 2012).
ovarian carcinoma (continued). "The study showed 47 potential tumor-specific lectin reactive biomarkers for ovarian cancer; periostin and thrombospondin were presented as tumor-specific glycan changes that can be used to distinguish ovarian cancer patient serum from normal serum." (PMID 22084691, 2011). "Another report showed POSTN to be ranked among the top upregulated genes in ovarian cancer and GBM in both Agilent and Affymetrix microarray platforms." (PMID 21998659, 2011). "Periostin is expressed predominantly in fetal tissues and also in ovarian cancer, where it binds αVβ3/αVβ5 integrins and promotes cellular motility." (PMID 19146682, 2009). "Periostin (POSTN) is a secreted extracellular matrix protein, likewise induced by TGFβ and strongly connected to the enhancement of motility, invasion and metastasis of colorectal and ovarian cancer cells." (PMID 39695086, 2024). "Furthermore, POSTN was able to promote resistance to carboplatin and paclitaxel in ovarian cancer cells." (PMID 38942020, 2024). "POSTN is highly expressed in stromal components, especially fibroblasts, of ovarian cancer." (PMID 38601538, 2024). "Similarly, high levels of POSTN in ascetic fluids of ovarian cancer patients correlated with high CD163+ TAM recruitment and with decreased relapse-free survival." (PMID 38942020, 2024). "In the present study, we report that periostin is expressed in both stromal tissues and cancer cells and that expression is frequently increased in recurrent ovarian cancer as compared to the matched primary ovarian cancer from the same patient." (PMID 38049490, 2023). "Recombinant POSTN promotes resistance to carboplatin and paclitaxel in ovarian cancer cells." (PMID 36172351, 2022). "Yue.al reported that stromal Periostin could fuel the migration and invasion of ovarian cancer cells by binding to integrin αvβ3 and subsequently activating the PI3K/Akt pathway and inducing the EMT." (PMID 35915456, 2022). "Co-culture of A2780 ovarian cancer cells with THP-1-derived macrophages increases the expression of POSTN and its secretion from ovarian cancer cells, which could also be induced by TGF-β secreted from macrophages." (PMID 36550569, 2022). "As such, pathways modulated by DDR2 and POSTN can represent therapeutic targets in ovarian cancer." (PMID 35884543, 2022). "Stromal DDR2 is highly correlated with stromal POSTN expression in ovarian cancer patient tumors." (PMID 35884543, 2022). "POSTN is a secreted protein, which can bind to αvβ3 and αvβ5 integrins on ovarian cancer cells." (PMID 36550569, 2022). "Expression of POSTN was found to be elevated in highly invasive ovarian cancer cells." (PMID 36550569, 2022). "However, the biological function of FAM48B1 is rather unclear, and FN1 has been quite well characterized, so we decided to focus on evaluating the role of POSTN in ovarian cancer progression and metastasis." (PMID 36550569, 2022). "For example, many TGF-β signaling-related genes derived from CAFs play important roles in the crosstalk between fibroblasts and ovarian cancer, including periostin (POSTN), collagen type XI alpha 1 (COL11A1), collagen triple helix repeat containing-1 (CTHRC1), and versican (VCAN)." (PMID 35681617, 2022). "In addition to POSTN expression in tumor cells, stromal POSTN has been found to have prognostic significance in various cancers, including ovarian cancer." (PMID 35884543, 2022). "To determine whether POSTN could mediate NF-κB activation in ovarian cancer cells, we examined the expression and phosphorylation status of proteins associated with the PI3K and NF-κB signaling pathways." (PMID 36550569, 2022). "POSTN expression significantly enhances angiogenesis and metastasis in ovarian cancer." (PMID 36077762, 2022). "In addition to affecting migration and invasion ability, we observed knockdown of POSTN led to decreased adhesion ability of cancer cells, an important property for peritoneal metastasis of ovarian cancer cells." (PMID 36550569, 2022).